GFAP (glial fibrillary acidic protein)
Diseases named in the same sentence as GFAP in open-access papers (continued):
Sharing a sentence is not in itself a finding about the gene and the disease.
Anxiety (continued). "At the end of the study, HFFD resulted in anxiety‐like behavior, reduced locomotor activity, neuroinflammation (increased brain GFAP, IL‐6, MCP‐1, IFN‐γ, TNF‐α), and systemic inflammation (increased plasma GFAP, IFN‐γ, TNF‐α, IL‐12p70, reduced plasma IL‐10)." (PMID 39619979, 2024). "The combination of MS and LPS had a synergistic effect on the anxiety-like behaviour, locomotor activity, and GFAP mRNA expression outcomes." (PMID 38397434, 2024). "We investigated the behavioral consequences of selective cortical GFAP+ cell depletion (achieved through artificial expression of the diphtheria-toxin receptor (DTR)) on anxiety, anhedonia, and helplessness." (PMID 37461693, 2023). "In aged rats, the HFHS diet impaired spatial learning, memory, and working memory and increased anxiety levels, associated with a reduction in the number of DCX cells and an increase in GFAP cells in the hippocampus." (PMID 36986100, 2023). "In the NSF test, used to measure anxiety‐like behaviour, GFAP‐Tk males presented an increased latency to feed when compared to WT males (unpaired two‐tailed t test, t = 6.2020, df = 17, p < 0.0001, Rsq = 0.69)." (PMID 34970787, 2022). "Previous data from our laboratory using the same animal model show that GFAP‐Tk male rats have an increased anxiety‐like behaviour, further entangling the anxiety domain exploration." (PMID 34970787, 2022). "Knockout of the GLT-1 gene in astrocyte using male transgenic GFAP-Cre mice results inincreased anxiety-like behaviors in the elevated plus maze." (PMID 34955780, 2021). "Potential correlations between MAP2 and GFAP positive signal (area fraction) and anxiety-like behaviors (time spent in the enclosed, safe arm of the EPM) were investigated." (PMID 34955781, 2021). "In young mice, antioxidants increased the anxiety of the GFAP-ApoE4 mice, suggesting an age-dependent response to interventions." (PMID 32630431, 2020). "To examine the role of GFAP-positive astrocytic GLT1 in anxiety-related fear, we trained mice with five tone and foot shock pairing on day 1, and then we performed the contextual and cued fear memory tests on day 2 and day 3, respectively." (PMID 32390810, 2020). "During the light-dark box test, both GFAP-Cre Hrh1f/f and CaMKII-Cre Hrh1f/f mice spent significantly more time in the illuminated compartment, a measure of reduced anxiety." (PMID 31712580, 2019). "Intra-LC injection of conditioned medium from cultured astrocytes treated with LPS increased GFAP expression, anxiety-like behavior and mechanical allodynia in both male and female mice." (PMID 28701953, 2017). "We found that MSSI sex-dependently activated astrocytes in the LC, as indicated by increased GFAP expression, with increases in anxiety-like behavior." (PMID 28701953, 2017). "The important point is that LC administration of supernatant derived from LPS-treated astrocytes increased anxiety-like behavior and GFAP expression in both male and female mice." (PMID 28701953, 2017). "The GCV treated GFAP-TK rats exhibited reduced anxiety on two novelty-suppressed feeding tests and a black/white alley emergence test." (PMID 24039591, 2013). "In a non-appetitively motivated black/white alley emergence test the GFAP-TK rats again exhibited decreased anxiety." (PMID 24039591, 2013). "The aim of the current investigation was to evaluate the impact of taVNS intervention applied at three discrete frequencies on locomotor activity, memory, anxiety‐like behaviour and hippocampal gene expression of GFAP, Iba1 and BDNF in animals subjected to morphine." (PMID 40183201, 2025). "Given that LXRβ is enriched in astrocytes cultures compared to neuronal cultures, a recent study used a GFAP promoter-mediated Cre-LoxP system to obtain conditional knockout mice of LXRβ in astrocytes and investigate the role of this astrocyte receptor in anxiety levels." (PMID 40141416, 2025).
Anxiety (continued). "This study reveals a novel mechanism by which ACTH mitigates anxiety-like behaviors and normalizes key astrocyte markers, including glial fibrillary acidic protein and aquaporin-4, following early-life seizures (ELS) in a melanocortin 4 receptor (MC4R)-dependent manner." (PMID 40015967, 2025). "Furthermore, another study showed that inhibition of activated astrocytes after inflammation was able to ameliorate anxiety and depressive-like behaviors induced by lipopolysaccharide in addition to decreasing GFAP and increasing BDNF levels in the brain." (PMID 40015967, 2025). "Meanwhile, although less likely, anxiety may also induce neuroinflammation—such as through the release of serum GFAP—which could potentially increase systemic inflammation and gastrointestinal susceptibility to H. pylori infection." (PMID 41210138, 2025). "Additionally, unpredictable chronic mild stress substantially increased GFAP immunoreactivity and promoted a more branched, reactive morphology in the hippocampus, which was correlated with increases in anxiety and anhedonic-like behaviors." (PMID 38990919, 2024). "Mice with a specific deletion of TNF from astrocytes (using GFAP-Cre combined with floxed TNF alleles) have an equivalent increase in anxiety-like behaviour following stress as their Cre negative littermates." (PMID 36104437, 2022). "NSF behavior has been tested in an independently generated GFAP-TK rat, however, anxiety-like effects observed in untreated rats in this strain suggest a random gene insertion effect on anxiety that precludes interpretation of neurogenesis-dependent effects on neophagia." (PMID 27257630, 2016). "GFAP-TK rats were significantly more likely to eat (8 out of 21, one rat untested) compared with wild type controls (1 out of 18, df = 1,37, P = 0.011, logistic regression), suggesting reduced anxiety in the transgenic group." (PMID 24039591, 2013). "Thus, we sought to determine if GFAP-DNSynCAM1 mice exhibit changes in measures of anxiety using paradigms involving avoidable and unavoidable anxiety-provoking stimuli." (PMID 22558465, 2012). "The GFAP-DNSynCAM1 mice also displayed reduced measures of anxiety in the acoustic startle test." (PMID 22558465, 2012). "In addition to ADHD-like impairments, GFAP-DNSynCAM1 mice exhibit reduced measures of anxiety, and increased impulsivity, two features observed in serotonin receptor 5HT1B KO mice, another model of ADHD." (PMID 22558465, 2012). "In addition, compared to GFAP-apoE3 mice, GFAP-apoE4 mice demonstrate impaired cognition and increased anxiety; common symptoms in AD patients." (PMID 22028984, 2011). "Future investigations should examine both peripheral and CNS levels of systemic inflammatory markers and GFAP in mouse models of H. pylori infection, with particular focus on whether modulation of these factors through human intervention can alter anxiety-like behaviors." (PMID 41210138, 2025). "Also, decreased AChE activity may contribute to triggering anxiety-like behaviors, followed by increased central nervous system-related glial fibrillary acidic protein (GFAP) and alpha-tubulin genes." (PMID 38792660, 2024). "GFAP-DNSynCAM1 mice also display high levels of basal activity in the dark period (the rodent's awake/active time) that are attenuated by the psychostimulant D,L-amphetamine, and reduced anxiety levels in response to both avoidable and unavoidable provoking stimuli." (PMID 22558465, 2012). "GH also reduced microglial (Iba-1) and astrocytic (GFAP) hypertrophy, restored MBP and β-III tubulin levels, enhanced Purkinje cell survival, and improved motor coordination and anxiety-like behavior in adulthood." (PMID 41226706, 2025). "Specifically, 7 days after intracerebroventricular (i.c.v.)infusion of IL-1β, male rats exhibited elevated anxiety levels in the OFT and EPM test, along with an increased expression of GFAP and elevated GABA content in PVN astrocytes." (PMID 40141416, 2025).
Anxiety (continued). "Behavioral assessments were used to evaluate anxiety- and depressive-like symptoms, and biochemical analyses measured oxidative stress markers, serotonin levels, MAO activity, BDNF, and GFAP as indicators of neuroinflammation in the prefrontal cortex." (PMID 40780966, 2025). "GFAP was negatively related to PTSD symptom severity, combat exposure, anxiety, stress, and alcohol use." (PMID 35217643, 2022). "This indicated that animals with lower levels of GFAP and MAP2 exhibited greater anxiety-like behaviors." (PMID 34955781, 2021). "In our study, we observed that potential interactions between serum GFAP and both SII and AISI levels could influence anxiety severity in H. pylori-positive patients." (PMID 41210138, 2025). "However, enhancing PFC GFAP+ cell activity was unable to reverse CRS-induced anxiety-like effects measured independently in the PhenoTyper and the NSF test or overall anxiety z-score." (PMID 37461693, 2023). "Mice with GFAP+ cell depletion showed no behavioral deficits in the FST or in any of the independent tests for anxiety-like behaviors (EPM, OF, NSF) or overall anxiety z-score." (PMID 37461693, 2023). "Altogether, we demonstrated that enhancing PFC GFAP+ cell activity reversed CRS-induced anhedonia- but not anxiety-like behavior." (PMID 37461693, 2023). "Overall, our results suggest that cortical GFAP+ cell depletion induce anhedonia-like but not anxiety- or helplessness-like deficits." (PMID 37461693, 2023). "Others have found a lack of GFAP expression after blast exposure, which corresponds with an anxiety-like phenotype." (PMID 35761393, 2022). "LZU-J-TSL6 was able to effectively increase the GABA content in the mice hippocampus (p < 0.0001) and restore some markers related to anxiety such as brain-derived neurotrophic factor (BDNF), glial fibrillary acidic protein (GFAP), and 5-hydroxytryptamine (5-HT)." (PMID 36429192, 2022). "As expected, CVS significantly increased anxiety- and depressive-like behaviors and corticosterone levels and decreased GFAP expression in astroglia, although this did not reflect a change in the total number of astroglial cells." (PMID 29907879, 2018). "Notably, the significant genotype–treatment effect for the light zone time, with the GFAP KI–ACTH treatment showing a significant effect compared with all other groups, suggests that the effect of treatment on reducing anxiety was more pronounced in the GFAP KI genotype group." (PMID 40015967, 2025). "However, GFAP+ astrocyte activation induced a mild decrease in anxiety-related behaviors in the open field, while our negative memory activation significantly increased anxiety." (PMID 38990919, 2024). "However, a clear link between the observed reductions in GFAP+ cell density and the development of anxiety- or anhedonia-like behavioral deficits has not been established." (PMID 37461693, 2023). "Conversely, activating PFC GFAP+ cell activity for 3 weeks using designer receptor exclusively activated by designer drugs (DREADDs) reversed chronic restraint stress-induced anhedonia-like deficits, but not anxiety-like deficits." (PMID 37461693, 2023). "Here, we used three anxiety‐focused tests and showed that GFAP‐Tk females do not have alterations in anxiety, exposing a differentiated disruption of behavioural domains that needs further exploration to disambiguate the differences derived from methodology from those derived from biology." (PMID 34970787, 2022). "Our results are consistent with results from other neurogenesis ablation models, such as the GFAP-TK mouse line, and also with a key message that emerged from a meta-analysis of the field: ablated neurogenesis leads to depressive-, but not baseline anxiety-like, behaviors." (PMID 26795203, 2016).
Anxiety (continued). "When anxiety levels in the elevated plusmaze were assessed in a cohort of 6-month-old GFAP-apoE male mice,in which the expression of apoE3 or apoE4 is targeted toastrocytes, GFAP-apoE3, but not GFAP-apoE4, male mice showed lessmeasures of anxiety in the elevated plus maze thanApoe−/− mice." (PMID 17710250, 2007). "Thus, the increased GFAP expression in the PFC and Iba-1 expression in the hippocampus we observed in response to MS exposure in the present study may have contributed to the behavioural deficits observed, including increased anxiety and reduced locomotor activity." (PMID 38397434, 2024). "Our previous results demonstrated that MSSI increased anxiety-like behaviors in female but not male mice and MSSI did not influence GFAP expression in the LC of male mice." (PMID 28701953, 2017). "The expression of GFAP did not change after CFA injection and/or FMNT treatment, indicating that the astrocytes were not involved in the modulation of anxiety, and that the anxiolytic effects of FMNT may be related to the inhibition of microglia activation by NF-κB p65 signaling pathway." (PMID 30961625, 2019).
Cerebral ischemia (78 papers, 2011 to 2025). Restriction of arterial blood supply to the brain associated with insufficient oxygenation to support the metabolic requirements of the tissue. "The live imaging of inflammation in bigenic reporter mice (GFAP-luciferase) revealed that sex and estrogen levels are strong determinants of astrocyte activation/response caused by cerebral ischemia." (PMID 25147799, 2014). "Post hoc analysis showed that BHD treatment elevated the cell number of Ki67+, Ki67/MAP-2+ and Ki67/GFAP+ in the peri-infarct cortex following cerebral ischemia." (PMID 40973940, 2025). "Both the astrocyte marker GFAP and the microglia marker Iba1 were significantly reduced when animals were treated with 3 mg/kg istradefylline following cerebral ischemia." (PMID 40565142, 2025). "Treatment with Gas effectively suppressed the excessive activation of GFAP, suggesting that Gas can modulate astrocytic activation and mitigate astrocyte‐mediated responses following cerebral ischemia." (PMID 40790939, 2025). "Cerebral ischemia stimulates the release of glial fibrillary acidic protein (GFAP) by astrocytes, which are the predominant glial cells in the brain." (PMID 37848698, 2024). "The presence of GFAP/Nestin+ cells suggests that cerebral ischemia induces developmental phenotypes with differentiation potential and changes the direction of differentiation within neuroglia cell populations." (PMID 39090706, 2024). "In the hippocampus and frontal cortex, an elevation of GFAP level was shown after global brain ischemia and subsequent three-day reperfusion." (PMID 39057034, 2024). "Changes in Lcn2 expression in GFAP-positive astrocytes indicate that exercise alters astrocytic features after cerebral ischemia." (PMID 36880055, 2023). "The expression of Iba-1 and GFAP can be used to observe the effect of EE on microglia and astrocytes after cerebral ischemia." (PMID 37688770, 2023). "The number of GFAP-positive cells increased in the acute phase of cerebral ischemia and decreased after POD6." (PMID 36880055, 2023). "Cerebral ischemia caused a reduction in neuron-related NeuN protein, with increases in both macrophage/microglia-related CD68 protein and astrocyte-related GFAP protein levels." (PMID 34073455, 2021). "GFAP upregulation after brain ischemia will be weak at 24h post-injury but will increase rapidly during the first week, while the number of GFAP-positive astrocytes increases within the first two weeks." (PMID 33672842, 2021). "Usnic acid significantly reduced caspase-3, glial fibrillary acidic protein- positive and ionized calcium-binding adaptor molecule 1-positive cells (P<0.001) and enhanced spatial memory disorders (P<0.05) due to brain ischemia." (PMID 32963745, 2020). "We see a significant increase in GFAP-C6 at 72 hours after CA suggesting that global cerebral ischemia affects processes related to the cleavage of GFAP by caspase-6." (PMID 31693684, 2019). "The activation of astrocytes, presenting as astrocyte proliferation, morphological change, and enhanced expression of GFAP, can be induced by cerebral ischemia, inflammation, and oxidative stress." (PMID 31681297, 2019). "Cerebral ischemia considerably enhanced the GFAP staining in the PBS group as control (90±10) compared with the sham group (42±1) (P<0.001)." (PMID 31031895, 2019). "There is a close link between enhancing expression of glial fibrillary acidic protein (GFAP) and cerebral ischemia." (PMID 31684142, 2019). "Under the cerebral ischemia condition, astrocytes are activated, which is characterized by an increase in glial fibrillary acidic protein (GFAP) expression and elongation of neural processes, as well as secretion of interleukins (ILs)." (PMID 30227858, 2018). "Western blotting analyses showed that the expression of GFAP increased at day 5 and day 10 after transplantation, respectively, in the brain of cerebral ischemia rats treated with BMSCs or mild hypothermia alone." (PMID 30067742, 2018).